DRD1 (dopamine receptor D1)
Diseases named in the same sentence as DRD1 in open-access papers (continued):
Sharing a sentence is not in itself a finding about the gene and the disease.
Anxiety (43 papers, 2014 to 2025). Intense feelings of nervousness, tension, or panic often arise in response to interpersonal stresses. "Elevated DRD1 expression could provide an explanation for this effect, as increased DRD1 activity has been linked to reduced anxiety." (PMID 38611750, 2024). "Hare and colleagues found that selectively activating neurons containing D1 dopamine receptors (Drd1) in mPFC quickly reduced symptoms of depression and anxiety in animals, with effects lasting well beyond the stimulation period." (PMID 40026920, 2025). "Baseline effects of Drd1-dCas9-p300 expression on anxiety-like behavior was further assessed using the elevated plus maze." (PMID 40707359, 2025). "Nevertheless, direct investigation into DRD1 expression and its specific effects on anxiety and hyperactivity following chronic TBI is required for a more comprehensive understanding." (PMID 38611750, 2024). "We observed that injection of the DRD1 antagonist SCH23390 or the DRD2 agonist quinpirole into the BLA contributed to anxiety-like behaviors in naive mice." (PMID 35696012, 2022). "To further demonstrate the role of DRD1 and DRD2 in the BLA in spared nerve injury (SNI) model-induced anxiety-like behaviors, we injected the DRD1 agonist SKF38393 or the DRD2 antagonist sulpiride into the BLA." (PMID 35696012, 2022). "In conclusion, we have demonstrated a novel mechanism by which DRD1 and DRD2 in the BLA play different roles in neuropathic pain-induced anxiety-like behaviors through decreased DRD1 and increased DRD2." (PMID 35696012, 2022). "Taken together, these findings suggest that inhibition of DRD1 in the BLA contributes to anxiety-like behaviors in naive mice and that EA reverses this effect." (PMID 35696012, 2022). "Our results showed that in the physiological state, antagonizing DRD1 in the BLA led to anxiety-like behaviors, which were alleviated by a DRD1 agonist or EA treatment in naive mice." (PMID 35696012, 2022). "EA alleviated anxiety-like behaviors to an extent similar to that of the DRD1 agonist and DRD2 antagonist." (PMID 35696012, 2022). "Owing to decreased transmembrane Drd1 insertion, the mutant rats displayed normal basic motoric and neurological parameters, as well as locomotor activity and anxiety-like behaviour." (PMID 27483345, 2016). "DRD1 triggers a cascade of intracellular events through the adenylate cyclase/cyclic adenylate/protein kinase A (AC/cAMP/PKA) pathway, with the activity of PKA associated with anxiety." (PMID 38611750, 2024). "Moreover, the activity of dopamine receptor D1 in the ventral tegmental area is also crucial to regulate anxiety and depression, which is negatively related to the progression of anxiety and depression." (PMID 39012662, 2024). "EA alleviates anxiety-like behaviors by activating DRD1 or antagonizing DRD2 in the BLA." (PMID 35696012, 2022). "EA also activated DRD1 or inhibited DRD2 in the BLA to alleviate anxiety-like behaviors." (PMID 35696012, 2022). "DRD1 plays a critical role in regulating anxiety, as shown by previous studies." (PMID 35696012, 2022). "Electroacupuncture (EA) is commonly used to treat chronic pain and emotional disorders, but it is still unclear whether EA plays a role in analgesia and anxiety relief through DRD1 and DRD2 in the BLA." (PMID 35696012, 2022). "In the pathological state, not only activation of DRD1 in the BLA but also EA treatment could relieve anxiety-like behaviors induced by SNI in mice." (PMID 35696012, 2022). "EA stimulation relieves anxiety-like behaviors in SNI mice by activating DRD1 in the BLA." (PMID 35696012, 2022). "Finally, differential deletion of SHANK3 either affecting DRD1- or DRD2-positive neurons (ex4-22|ALL-Drd1Cre or -Drd2Cre) resulted in a minor anxiety-like phenotype and increased repetitive behavior, respectively." (PMID 34784886, 2021).
Anxiety (continued). "At the end of the 12-week experiment, anxiety-like behavior was evaluated by the light/dark box test; compulsive-like behavior by Marble burying, transcriptional regulation of genes Lrrk2, Tlr4, Nfat, Drd1, Drd2, Il6, Il1β, Il10, and iNOS by RT-qPCR; and inflammatory markers by flow cytometry." (PMID 37063320, 2023). "Elevated anxiety levels were also replicated in conditional KO-strategies, inducing SHANK3 deficiency in somatosensory neurons or cells derived from the caudal embryo (ex13-16|PDZ-AdvillinCre or -Cdx2Cre), but also in GABAergic (ex14-16|PDZ-ViaatCre) or DRD1-positive neurons (ex4-22|ALL-Drd1Cre)." (PMID 34784886, 2021). "The fructose groups showed high levels of expression of DRD1 and DRD2 receptors, which play a key role in anxiety regulation." (PMID 36901891, 2023). "Together, these results suggest that both the activation of DRD1 in the BLA and EA stimulation attenuate SNI-induced anxiety-like behaviors." (PMID 35696012, 2022). "Previous studies have suggested that both DRD1 and DRD2 regulate anxiety, but they do so through different mechanisms." (PMID 35696012, 2022). "We next determined that DRD1 in the BLA participates in alleviating hyperalgesia and anxiety-like behaviors induced by SNI in mice." (PMID 35696012, 2022). "Here, we used western blotting to examine the expression of DRD1 and DRD2 and pharmacological regulation combined with behavioral testing to detect anxiety-like behaviors." (PMID 35696012, 2022). "Overall, no baseline differences in anxiety-like behavior were detected between Drd1-Cre:dCas9-p300 mice and their genotype littermates." (PMID 40707359, 2025). "Naïve Grp-/- mice displayed normal anxiety and pain sensitivity, consistent with normal expression of immediate-early genes (IEG; c-Fos and Arc) and dopamine-related genes (Drd1, Drd2, Th and Nurr1) in the BLA and VTA of naïve Grp-/- mice." (PMID 39580604, 2025). "DRD1 and DRD2 in the BNST regulate anxiety, fear, and addiction." (PMID 39841059, 2025). "We found that both activation of DRD1 and inhibition of DRD2 could alleviate SNI-induced anxiety-like behaviors, and EA had a similar effect of alleviating anxiety." (PMID 35696012, 2022). "Intra-BLA administration of DRD1 antagonist or DRD2 agonist in naive mice induced anxiety-like behaviors, with no change in PWTs." (PMID 35696012, 2022). "Our study demonstrated that the protein levels of DRD1 were significantly decreased and those of DRD2 were increased in the AMY after SNI surgery, which suggested that DRD1 and DRD2 in the AMY have opposite effects on anxiety behaviors." (PMID 35696012, 2022). "Injection of DA receptor agonists or antagonists into LHb showed that activation or inhibition of DRD1 but not DRD2 in LHb increased anxiety-like behavior, but decreased depressive-like behavior in rats." (PMID 36059987, 2022). "In the EPM conducted 48 h after photostimulation, Drd1-Cre mice spent more time in the open arms and displayed a trend for increased open arm entries, indicating reduced anxiety; there were no changes in closed arm entries or total arm entries." (PMID 30644390, 2019). "Dopamine receptor D1 (DRD1) and dopamine receptor D2 (DRD2) in the basolateral amygdala (BLA) have been implicated in mediating anxiety-related behaviors, but their potential roles in the BLA in neuropathic pain-induced anxiety have not been examined." (PMID 35696012, 2022). "Next, we first wondered whether the intra-BLA administration of the DRD1 antagonist SCH23390 in naive mice would affect PWTs and anxiety-like behaviors and whether EA would alleviate anxiety-like behaviors in a manner similar to that of the DRD1 agonist SKF38393 in naive mice." (PMID 35696012, 2022). "Both overexpression of DRD1 and optogenetic stimulation of DRD1, but not DRD2, within the PFC, have shown similar reductions in anxiety-like behavior, as indicated by a higher number of open arm entries in the elevated plus maze." (PMID 38611750, 2024).
Anxiety (continued). "Both activating DRD1 and antagonizing DRD2 in the BLA attenuated SNI-induced anxiety-like behaviors, but neither had an effect on mechanical allodynia." (PMID 35696012, 2022). "However, a potential role of DRD1 and DRD2 in the BLA in neuropathic pain-induced anxiety has not been examined in the spared nerve injury (SNI) model." (PMID 35696012, 2022).
depression (36 papers, 2009 to 2025). "More specifically, some variations of miR-504, rs686, affecting DRD1 regulation, have been found associated with higher depression scales." (PMID 34829888, 2021). "Similarly, a recent clinical study provides new evidence on the presence of a functional polymorphism in the dopamine receptor D1 (DRD1) to be modulated by miR-504 and associated with depression." (PMID 31861723, 2019). "The aims of this study were to analyze associations of dopamine receptor genes (DRD1-5) with Major Depressive Disorder (MDD) and nicotine dependence (ND), and to investigate whether ND moderates genetic influences on MDD." (PMID 24927283, 2014). "Decreased DRD1 expression levels are found in patients with emotional disorders including depression." (PMID 39962033, 2025). "Recently, an increasing number of articles have highlighted the ability of both DRD1 and DRD2 to form heterodimers, and a growing body of evidence has linked D1-D2 heterodimers to drug addiction, Parkinson’s disease, schizophrenia, depression, and anhedonia." (PMID 36059987, 2022). "The second module control downstream FOS to treat depression by targeting the DRD1/DRD5--GNAQ--PLCB1--DAG--PRKCA cascade reaction." (PMID 34867413, 2021). "The second module is target to the DRD1/5-GNAQ-PLC B1-DAG-PRKCA cascade signal to control the downstream FOS to treat depression." (PMID 34867413, 2021). "The expression of striatal DRD1 was significantly decreased, while DRD2 expression was dramatically increased in the aged WDR45cKO mice, which may be associated with depression-like behavior." (PMID 39183331, 2024). "Lower DRD1 levels are found in patients with affective disorders, including depression." (PMID 33863350, 2021). "CIS-induced decreases in DRD1 and GABRG2 levels might be involved in the increase in susceptibility to depression in this context." (PMID 33863350, 2021). "Indeed, among the downregulated genes, we identified the gene coding for dopamine receptor D1A (Drd1a) involved in depression." (PMID 32742258, 2020). "In contrast, other mechanisms involved in the regulation of DRD1 translation or miR-504 could have regulated the expression of other genes responsible for the role of miR-504 in stress-induced depression." (PMID 23922862, 2013). "In contrast, DRD2 mRNA and DRD2 protein expression negatively correlated with immobility time, suggesting that DRD2 may play a more important role than DRD1 in the development of stress-induced depression." (PMID 23922862, 2013). "However, the molecular mechanisms underlying decreased DRD1 and DRD2 expression in stress-induced depression have yet to be fully elucidated." (PMID 23922862, 2013). "Therefore, the observed alterations in miR-504, DRD1, and DRD2 expressions should only be associated with depression-like phenotype." (PMID 23922862, 2013). "Thus, CIS-induced decreases in DRD1 and GABRG2 levels might be involved in susceptibility to depression in middle-aged female mice." (PMID 33863350, 2021). "The relationship of NAc neurons in rats that co-express DRD1 and DRD2, forming D1-D2 heterodimers, with depression is unclear." (PMID 36059987, 2022). "l-SPD, which has a unique pharmacological profile of DRD1 agonism and DRD2 antagonism exerted antidepressant-like effects on the CMS model of depression." (PMID 36059987, 2022). "The expression level of the 5-HT1A, DRD1, ADRA-2A, GABA-A α1, CNR1, NR3C2, NOD1, NLRP3 and MC4R; BDNF levels, glial activity and intestinal permeability were determined in chronic stress-induced depression in rats." (PMID 40281288, 2025). "DRD1 and DRD2 are expressed on glutamatergic PYR neurons in the PFC, but the role of D1 and D2 receptors expressed in PFC PYR in depression and antidepressant responses is largely unknown." (PMID 36059987, 2022).
depression (continued). "Notably, it has been reported that Drd1 has antidepressant effects, and the mice in our study did not exhibit depression-like behavior in the FS test; thus, it is possible that Drd1 receptors are associated with the FS outcomes in our mouse model." (PMID 38336912, 2024). "However, how DRD1 and the levels of the GABAA receptors GABRA1, GABRB2 and GABRG2 change in depression in middle age remains unclear." (PMID 33863350, 2021). "miR-504 may mediate the downregulation of DRD1 and DRD2 expression in the nucleus accumbens, but DRD2 not DRD1 is involved in stress-induced depression in the animal models tested in this study." (PMID 23922862, 2013).
Dyskinesia (33 papers, 2013 to 2026). A movement disorder which consists of effects including diminished voluntary movements and the presence of involuntary movements. "In addition, dopamine precursor molecule 3,4-dihydroxyphenyl-l-alanine (l-DOPA)-induced dyskinesias and up-regulation of DeltaFosB can be blocked by genetic inactivation of DRD1." (PMID 23873704, 2013).
Cognitive impairment (25 papers, 2015 to 2025). Abnormal cognition is characterized by deficits in thinking, reasoning, or remembering. "Whether DRD1 downregulation can cause cognitive deficits in the hyperdopaminergic state is the subject of discussion, and further studies are needed to answer this question." (PMID 35370807, 2022). "This focus was motivated by previous findings demonstrating that Per2 KO leads to cognitive impairments through DRD1-PKA-CREB signaling changes, and METH treatment restores both cognitive function and gene expression levels." (PMID 39002057, 2025). "In accordance with our results, it has been reported that DRD1, DRD2, DRD3, DRD4, and SLC2A9 are associated with cognitive performance or cognitive impairment." (PMID 34285142, 2021). "In accordance with disrupted GHSR/DRD1 heteromerization, aged mice showed reduced synaptic density in their hippocampal CA1 region, an aging-sensitive brain area, the dysfunction of which is associated with age-related cognitive deficits." (PMID 37212281, 2023). "Increased expression of dopamine receptors may lead to signaling abnormalities and subsequent cognitive impairment if translational controls break down and allow for the increased DRD1 and 5 transcripts to produce more protein." (PMID 36056313, 2022).
Hypertension (19 papers, 2011 to 2025). The presence of chronic increased pressure in the systemic arterial system. "In Dat we capture 12 indications for Propranolol and 17 disease associations for DRD1, with one indication, Hypertension, involved in both an indication association for Propranolol and a disease association for DRD1." (PMID 26844016, 2016). "In humans, the DRD1 gene presents a A-48G polymorphism associated to hypertension in a Japanese population." (PMID 23905040, 2012). "The major finding of our work is the identification of the -48A/A variant of the DRD1 gene as a potential risk factor for kidney damage in hypertension." (PMID 23905040, 2012). "In conclusions, the DRD1 A-48G polymorphism identifies a class of H that is prone to hypertension related kidney alterations." (PMID 23905040, 2012). "To further explore whether DRD1 variant can differently interfere with the effects of high blood pressure on kidney function, we selected 15 patients carrying 2 copies of either the A-48 or the G-48 DRD1 alleles." (PMID 23905040, 2012). "In conclusion, our data support the role of the DRD1 as a genetic marker for hypertension related kidney damage and provide molecular bases for the notion that the hypertension related target organ damage is modified by genotypes." (PMID 23905040, 2012).
breast cancer (13 papers, 2016 to 2025). A primary or metastatic malignant neoplasm involving the breast. "We present in this study an agonist of DRD1, A77636, upregulated the phosphorylation of eIF2α and inhibited proliferation and motility of breast cancer cells as well as bone loss and weakening." (PMID 28374823, 2017). "DRD1 was a gene associated with breast cancer and lung cancer." (PMID 35401884, 2022). "For example, in breast cancer, DRD1 agonists have been shown to inhibit breast cancer cell growth in vitro, reduce cancer stemness and cell mobility in vitro, and reduce tumor growth and lung metastasis in vivo." (PMID 38572507, 2024). "In the context of breast cancer bone marrow metastasis, a selective agonist of DRD1, A77636, suppressed breast cancer proliferation and migration." (PMID 34717619, 2021). "DRD1 was highly expressed on tumour cells of approximately 50% of colon cancers, ovarian cancers, breast cancers, renal cell carcinomas and GIST samples." (PMID 31478179, 2020). "Contradictory results have also been published for dopamine receptor D1 (DRD1), as both inhibition as well as stimulation of tumour growth has been reported upon receptor activation in animal models of ovarian cancer and breast cancer." (PMID 31478179, 2020). "Another study showed that variants in DRD1 were relevant to the persistent and nonpersistent pain phenotypes in postsurgery breast cancer patients." (PMID 34717619, 2021). "In breast cancer, DRD1 was highly expressed on endothelial cells of 7 out of 12 samples." (PMID 31478179, 2020). "DRD1 induces breast cancer cell apoptosis by activating the DRD1/cGMP/PKG pathway." (PMID 27997578, 2016). "We also detected the expression levels of DRD1 in four cell lines (4T1Br, 4T1.2, MDA-MB-231, and EO771 mammary tumor cells)." (PMID 34031366, 2021). "A screening of ~1,000 biologically active compounds revealed that a selective agonist of dopamine receptor D1 (DRD1), A77636, inhibited proliferation of 4T1.2 mammary tumor cells as well as MDA-MB-231 breast cancer cells." (PMID 28374823, 2017). "Similar results were obtained in another study, suggesting that DRD1 overexpression has a negative effect on prognosis in patients with advanced breast cancer." (PMID 36091153, 2022).